BRCA1 (BRCA1 DNA repair associated)
Diseases named in the same sentence as BRCA1 in open-access papers (continued):
Sharing a sentence is not in itself a finding about the gene and the disease.
cancer (continued). "This opens a new therapeutic possibility for cancers with somatic inactivation of HR pathway genes, which will be tested in a recently opened phase I/II trial in BRCA1/2 deficient patients (NCT02719977)." (PMID 28211448, 2017). "Women with BRCA1 or BRCA2 gene mutations should undergo annualbreast cancer screening with magnetic resonance imaging from theage of 25 onward, as should women who have first-degreerelatives with a proven mutation (category Arecommendation)." (PMID 28894332, 2017). "Taken together, DRIP-seq and IF using independent cohorts of fresh and FFPE clinical samples, respectively, lead us to the same conclusion that BRCA1 mutation carriers are associated with luminal cell-specific R-loop accumulation in cancer-free breast tissue." (PMID 28649985, 2017). "On this day, the news magazine, New Scientist, published the article, “Counting genetic mutations predicts how soon you’ll get cancer”, which prominently featured BRCA1 in its lead paragraph." (PMID 29267345, 2017). "Considering that BRCA1/2 genes exhibit the highest rate of mutations (50%) in patients with breast and OC, patients with double cancers should be intensively aware of genetic testing." (PMID 28961279, 2017). "Given that this therapy will be approved for patients with BRCA-deficient cancer caused by somatic events, diagnostic demand is expected to increase for the analysis of BRCA1/2 somatic mutations and copy number alterations." (PMID 29383094, 2017). "Cancer Australia recommends consideration of RRSO by BRCA1 and BRCA2 mutation carriers at around the age of 40 years and individualised discussion for other women at high risk in the absence of a gene mutation." (PMID 28285341, 2017). "The BRCA1ness signature, on the other hand, was developed as a classifier to identify cancers exhibiting a BRCA1-mutated copy number profile." (PMID 28948212, 2017). "We have discovered two related small molecule drugs CX-5461 and CX-3543 that are able to selectively kill BRCA1/2 deficient cancer cells, one of which, CX-5461, is currently in advanced stages of phase I safety testing in humans." (PMID 28211448, 2017). "Similar to BRCA1/2 deficient cancers, mutation in the BAP1 gene leads to a deficient HR pathway and increases the reliance on other DNA repair pathways." (PMID 28756516, 2017). "The majority of published studies assessing the psychosocial impact of genetic testing for cancer susceptibility have focused on families with a known pathogenic variant in the BRCA1/2 genes." (PMID 28720130, 2017). "For effective homologous recombination repair, DNA requires functional heterozygous breast cancer genes (BRCA) which encode BRCA1/2." (PMID 29214031, 2017). "We conducted survival analyses to estimate the risk of cancer among relatives of carriers of BRCA1/2 mutations, and the penetrance of specific Colombian BRCA1/2 founder mutations." (PMID 28680148, 2017). "Genetic testing has implications for precision prevention, as a woman who has inherited a BRCA1 or BRCA2 mutation can reduce her cancer risk through risk‐reducing surgeries 12, and also receive enhanced screening to promote early detection." (PMID 28627138, 2017). "By contrast, haploinsufficiency for the related cancer suppressor, BRCA1, suffices to cause defects in stalled replication fork repair or integrity following HU exposure." (PMID 28575672, 2017). "It is also the first report on the prevalence of LGRs in BRCA1/2, and on the cancer risk conferred by specific Colombian BRCA1/2 founder mutations." (PMID 28680148, 2017). "BRCA1/BRCA2-associated cancer risk management includes increased cancer surveillance and risk reduction strategies." (PMID 28780755, 2017).
cancer (continued). "These inhibitors show efficacy in cancer cells with HR deficiency (HRD) including non-BRCA1/2 mutant tumours that carry mutations in genes involved in the HR pathway, since the accumulation of damaged DNA eventually leads to cell death." (PMID 28117679, 2017). "It is now more than ten years since the publication of the first preclinical evidence of PARP inhibitor synthetic lethality in BRCA1/2 mutation cancers." (PMID 28454085, 2017). "Cancers in 31 (83.8%) of the 37 women occurred in mutation carriers—24 (64.9%) were BRCA1 carriers and seven (18.9%) were BRCA2 carriers." (PMID 28240969, 2017). "It is now clear that cancer predisposition factors such as BRCA1/2 and the FA pathway do mitigate transcription–replication conflicts at R-loops to promote genome maintenance in cells." (PMID 28098815, 2017). "Identification of important gene mutations, such as BRCA1/2 that drive carcinogenesis, helped pave the way for precision diagnosis in cancer." (PMID 29872710, 2017). "The great majority has received a negative test result, yet some still harbor an undiscovered pathogenic BRCA1 or BRCA2 mutation (due to limited sequencing) or a pathogenic mutation in another cancer susceptibility gene." (PMID 28281021, 2017). "The association between BRCA1 P871L polymorphism and cancer risk has been investigated in a growing number of studies, but the conclusions are not conclusive." (PMID 28427168, 2017). "For cancer preventive options, risk-reducing mastectomies and salpingo-oophorectomies are effective in carriers of pathogenic BRCA1/2 mutations." (PMID 29383094, 2017). "There is great interest in understanding how inherited impaired functionality of cancer-relevant pathways shapes tumor phenotypes, as has been previously demonstrated for bMMRD and BRCA1 germline mutations." (PMID 28606096, 2017). "KPNA2 is shown to participate in the translocation of cancer-associated cargo proteins, such as Chk2, BRCA1, NBS1 and many others." (PMID 27974678, 2017). "The pooled results indicated that BRCA1 gene P871L variant decreased risk of overall cancer (homozygous model: odds ratio (OR) = 0.89, 95%confidence interval (CI) = 0.79-1.00; recessive model: OR = 0.89, 95% CI = 0.80-0.99)." (PMID 28427168, 2017). "We reported that immortalized human embryonic kidney (HEK293) cells as well as oncosuppressor gene-deficient human cells (BRCA1-KO fibroblasts) undergo malignant transformation when exposed to cancer patients’ sera." (PMID 28854931, 2017). "In cancers that lack homologous repair capacity due to BRCA1/2 or ATM dysfunction or loss, PARP inhibitors can lead to cancer cell death via mechanisms of synthetic lethality." (PMID 28993799, 2017). "For example, PARP inhibitors that target BRCA1/2 defects underlying HRR-deficiencies are also effective at killing cancer cells harboring defects in additional HRR genes, like RAD51, ATM, ATR, CHEK1, and RAD54B." (PMID 29104272, 2017). "PARP1 inhibition in BRCA1-deficient cancers results in collapsed replication forks and genomic instability leading to mitotic catastrophe and ultimately cell death." (PMID 28756516, 2017). "We identified deletions overlapping two known cancer susceptibility genes, (BRCA1 and BLM), and a duplication overlapping SMARCB1, associated with risk." (PMID 28302160, 2017).
cancer (continued). "In summary, our study suggests that NELF-dependent Pol II pausing is a previously unappreciated contributor to tumour development in BRCA1-deficient breast epithelium, which offers a potential cancer risk-assessing and -reducing tool." (PMID 28649985, 2017). "The evidence of an association of BRCA1/2 alterations with cancers in sites other than breast and ovary is of potential great relevance for several reasons." (PMID 28559958, 2017). "Reduced expression levels of the BRCA1 protein or BRCA1 mutations, compounded with insufficient lesion repair, provide a tipping point toward cancer induction." (PMID 28262780, 2017). "Many cell regulators and DNA damage response players, such as cyclinD1 29, 30, PLK1 31, 32 and BRCA1 20, 33, are mutated or dysregulated in cancers." (PMID 28058814, 2017). "Rapamycin has also been shown to overcome resistance to poly (ADP-ribose) polymerase (PARP) inhibitor in BRCA1-deficient cancers." (PMID 29152062, 2017). "Since a high percentage of the East Asian population carries a dominant‐negative allele of the aldehyde‐catalyzing enzyme ALDH2, studies investigating cancer risk associated with BRCA1 and BRCA2 mutations in this population will be important." (PMID 28835508, 2017). "Genetic tests of cancer predisposition genes, BRCA1 and BRCA2, inform significant clinical decisions for both physicians and patients." (PMID 28782058, 2017). "Different cancer types display different mutation signatures that are associated with different factors such as aging, smoking or BRCA1/2 mutations." (PMID 28978093, 2017). "A phase II trial of olaparib monotherapy for patients with germline BRCA1/2-mutated advanced cancer included 23 patients with PDAC and reported a response in 5 patients (21.7%); complete response in 1 (4.3%), and partial response (PR) in 4 (17.4%)." (PMID 29069866, 2017). "The present study demonstrates that there are large differences in the absolute cancer risks between BRCA1 and BRCA2 mutation carriers with higher vs lower values of the PRS." (PMID 28376175, 2017). "Assessment of the tumors of HG-SOC patients indicates that loss of the normal copy of BRCA1/2 is observed in the majority of germline BRCA1/2 mutations, consistent with this being an early event in the development of these cancers." (PMID 28525389, 2017). "A common phenotypic presentation of many known cancer predisposition genes, such as BRCA1/2, includes embryonic lethality in homozygote knockouts and increased cancer incidence in heterozygotes, which are reported in mouse model studies of some of these genes." (PMID 28591191, 2017). "Despite the good response of BRCA1/2‐mutated cancers to olaparib, acquired resistance is observed both in patients and GEMMs." (PMID 28028012, 2017). "RRSO has proven efficacy, with a reduction in “ovarian cancer” risk of 79–85%, and it is associated with lower cancer-specific and all-cause mortality in BRCA1 and BRCA2 mutation carriers." (PMID 28285341, 2017). "Our data suggest that the CX drugs, and possibly other G4 stabilizers have the potential to treat cancers deficient for BRCA1, BRCA2, NHEJ pathway members and some other genes involved in DNA damage repair and DNA replication." (PMID 28211448, 2017). "In conclusion, it is worth noting that carriers of germline mutations in the BRCA1 gene have vital cumulative risk much higher than the population for the development of cancer." (PMID 27926510, 2017). "In recent years, HR repair of double-strand DNA breaks has become a target for cancer therapy because BRCA1/2-deficient cancers are recognized as a target for a class of drugs known as PARP (poly (ADP-ribose) polymerase) inhibitors." (PMID 28073364, 2017). "We then examined the ability of MPH to suppress growth and proliferation of 11 cancer cell lines harboring well-characterized different deficiencies in the HR pathways, including BRCA1−/−, BRCA2−/−, PTEN−/− and EWS-FLI1." (PMID 27926532, 2017).
cancer (continued). "Mutations in BRCA1/2 have been confirmed to give rise to multiple cancers including pancreatic adenocarcinoma." (PMID 28415599, 2017). "In particular, two Single Nucleotide Polymorphisms (SNPs) in the OGG1 and NEIL2 genes were identified as cancer risk modifiers for BRCA1 and BRCA2 mutation carriers, respectively." (PMID 29383107, 2017). "PARP inhibitors (PARPi), an emerging class of drugs, are synthetically lethal against BRCA1/2-deficient cancer cells." (PMID 28055979, 2017). "Enhanced sensitivity to PARP inhibition has been reported in BAP1−/− cells compared with BAP1+/+ and BAP1+/− cells, as well as in cancer cells harboring inactivating mutations in BRCA1 or-2." (PMID 28122578, 2017). "Somatic mutations had >80% biallelic inactivation frequency and were predominantly clonal, suggesting that BRCA1/2 loss occurs early in the development of these cancers." (PMID 28525389, 2017). "We saw the same trend in families with a BRCA1 mutation, but had concluded at that point that the probable reason was the cancer-risk difference." (PMID 27804060, 2017). "Taken together these data show that cancer exosomes express proteins, which enable them to interact with receptors, de novo expressed on the membrane of BRCA1 mutated fibroblasts." (PMID 28854931, 2017). "Since the identification of the BRCA1/2 cancer susceptibility genes in 1994, there have been significant advances in our knowledge of the cancer risks for mutation carriers." (PMID 28936272, 2017). "FANCD2 also stabilizes stalled replication forks in BRCA1/2 deficient cancers, permitting their viability in extremely unstable genetic conditions." (PMID 28239445, 2017). "PARP inhibitors allow selective killing of cancer cells because the trapping/cytotoxic effect makes use of deficiencies in DNA repair systems that are unique to individual types of cancer (e.g. BRCA1/BRCA2-deficient tumors), as compared with normal tissue." (PMID 28978150, 2017). "A well-known example of this is the inhibition of the DNA repair component PARP1 in the BRCA1-deficient cancers result in replication fork collapse and mitotic catastrophe." (PMID 28756516, 2017). "Cancer-associated BRCA1-independent activities of BARD1 have been reported in various tumor cell lines." (PMID 29292755, 2017). "The mechanism by which RAD52 depletion causes synthetic lethality in BRCA1 mutant cancer cells depends on the 5′ endonuclease EEPD1, which normally functions to cleave stressed replication forks to initiate HR repair." (PMID 29145865, 2017). "Recently, PARP-1 inhibition has been demonstrated as an effective method for inducing synthetic lethality in cancers that have defective homologous recombination repair (HRR) pathway, such as cancers with BRCA-1/2 mutation." (PMID 27304949, 2016). "Screening for these three founder mutations is sufficient to capture nearly all inherited cancer risk in this population due to BRCA1 and BRCA2 mutations." (PMID 26867194, 2016). "Jolie carried a mutation in BRCA1, one of the cancer susceptibility genes linked to the so-called hereditary breast-ovarian cancer syndrome (HBOCS)." (PMID 26943589, 2016). "PARP1 inhibitors (PARPi) were found to be “synthetic lethal” in cancers deficient in BRCA1/2 with impaired homologous recombination." (PMID 26799421, 2016). "Together, these findings highlight the potential value for RANKL inhibition in BRCA1-associated cancers at the early stages of tumorigenesis." (PMID 27241552, 2016). "Using cancer cell lines genetically deficient in BRCA1 and/or PTEN and siRNA-mediated depletions, our study shows that PARG deficiency is neither synthetic lethal with BRCA1 nor with PTEN deficiency." (PMID 27375368, 2016).
cancer (continued). "DNA methylation can mimic the effects of both germline and somatic mutations for cancer predisposition genes such as BRCA1 and p16INK4a." (PMID 27902704, 2016). "BRCA1/BRCA2-deficient cancers are now recognized as the target for a class of drugs known as PARP (poly (ADP-ribose) polymerase) inhibitors." (PMID 27532258, 2016). "Chez les patientes ayant une mutation BRCA1 avec un premier cancer du sein, le risque du cancer controlatéral est évalué à 48% à l’âge de 50 ans et à 64% à l’âge de 70 ans." (PMID 28292084, 2016). "In cell lines, secondary somatic mutations in BRCA1- or BRCA2-mutant cancer cells can restore protein expression, reconstitute HR, and confer resistance to PARPi and platinum." (PMID 27634150, 2016). "When bound to its partner protein BARD1, BRCA1 is active as an E3 ubiquitin ligase, and cancer-predisposing germline mutations in the BRCA1 gene cluster in its N-terminal RING domain that underlies this activity." (PMID 27446204, 2016). "In contrast, F1662S and M1663K, two BRCA1 germline mutations identified in cancer patients, led to complete disruption of the dimer formation as the elution peaks of these two mutants in complex with Ab2p moved to the 1:1 complex position." (PMID 26778126, 2016). "Since no PARG inhibitors are available for in vivo studies, PARG was depleted by siRNA in several cancer cell lines, proficient or deficient for BRCA1 and/or PTEN." (PMID 27375368, 2016). "Cancer incidence in WT (2.6%) and BRCA1-mutated (45.9%) populations closely matched published epidemiologic rates." (PMID 27023391, 2016). "A human fibroblast cell line deficient for the oncosuppressor BRCA1 was developed to study its susceptibility to the oncogenic potential of cancer patient serum." (PMID 27179759, 2016). "The objective of this work was to quantify the contribution of the founder mutations BRCA2 c.156_157insAlu and BRCA1 c.3331_3334del for cancer etiology in unselected hospital-based cohorts of patients diagnosed with these rarer cancers in Portugal." (PMID 27532258, 2016). "We have previously found that the OGG1 SNP rs2304277may be a modifier of cancer risk in BRCA1 mutation carriers." (PMID 27015555, 2016). "AZD2281 Olaparib (kuDOS/LynparzaTM, AstraZeneca), used for oral administration, is the first inhibitor identified as single antitumoral agent in cancer associated with the BRCA1 or BRCA2 mutations." (PMID 27884198, 2016). "The minor alleles of all candidate causal variants in Peak 1 conferred increased risks of ER-negative BC and serous OC and increased risks of both cancers for BRCA1 mutation carriers." (PMID 27601076, 2016). "The expression levels of 236 cancer-associated genes, including BRCA1, were quantified using the Human Cancer Reference gene panel from the Nanostring Technologies nCounter Analysis System." (PMID 27534398, 2016). "A particular class of drugs, poly(ADP-ribose) polymerase-inhibitors (PARPi), has been shown to be effective for targeted treatment of cancers harbouring BRCA1 or BRCA2 mutations." (PMID 26745875, 2016). "PARP inhibitors are proved to be effective against BRCA1/2 mutated cancers and several phase III clinical trials are currently going on." (PMID 27220670, 2016). "In another single arm phase II trial olaparib has been evaluated in several kind of cancer with BRCA1/2 germline mutations." (PMID 27634150, 2016). "In BRCA1-deficient cancer cells, this stress-mitigating mechanism helps to prevent cell death, supporting cancer cell survival." (PMID 27590516, 2016). "Pathogenic mutations in the BRCA1/2 genes are known to be associated with increased risk for breast, ovarian and other cancers." (PMID 27375968, 2016). "Cancers with BRCA1/2 mutations are defective in HRR and are therefore hypersensitive to PARP inhibitors." (PMID 26713604, 2016). "Identification of individuals with BRCA1 germline mutations will enable physicians to optimize cancer management for this high risk phenotype." (PMID 27553291, 2016).